RNU6-701P (RNA, U6 small nuclear 701, pseudogene)
Gene: Small nuclear RNA gene on chromosome 5 (119,138,859 to 119,138,965, forward strand). Ensembl gene ENSG00000206786.
Homologues: Orthologues: chimpanzee U6 (98% identical), macaque U6 (93% identical), dog U6 (80% identical), mouse Gm23448 (77% identical), rat LOC120093307 (76% identical), rabbit U6 (71% identical). Paralogues in human: RNU6-1060P (91% identical), RNU6-1011P (90% identical), RNU6-842P (90% identical), RNU6-1158P (89% identical), RNU6-19P (89% identical), RNU6-24P (89% identical), RNU6-338P (89% identical), RNU6-727P (89% identical), RNU6-946P (89% identical), RNU6-949P (89% identical), RNU6-1124P (88% identical), RNU6-12P (88% identical), and 1290 more.